IFT122 (intraflagellar transport 122)
Description:
As a component of the IFT complex A (IFT-A), a complex required for retrograde ciliary transport and entry into cilia of G protein-coupled receptors (GPCRs), it is required in ciliogenesis and ciliary protein trafficking. Involved in cilia formation during neuronal patterning (By similarity).
Synonyms: SPG; WDR10; WDR140; WDR10p; FAP80; CFAP80; CED; CED1
Tractability: PROTAC: ubiquitination databases record sites on it; its protein half-life has been measured.
Gene: Protein-coding gene on chromosome 3 (129,429,607 to 129,520,510, forward strand). Ensembl gene ENSG00000163913.
Subcellular location: Cell projection, cilium; Cytoplasm, cytoskeleton, cilium basal body
Subcellular location (Human Protein Atlas): Cytosol; Mid piece; Primary cilium transition zone; Principal piece
Pathways (Reactome):
Organelle biogenesis and maintenance: Intraflagellar transport
Signal Transduction: Hedgehog 'off' state
Gene Ontology:
Molecular function: protein binding; protein carrier chaperone
Biological process: cilium assembly; intraciliary anterograde transport; intraciliary transport; protein localization to cilium; protein localization to non-motile cilium; camera-type eye morphogenesis; embryonic body morphogenesis; embryonic forelimb morphogenesis; embryonic heart tube development; embryonic heart tube left/right pattern formation; establishment of protein localization to organelle; intracellular signal transduction; intraciliary retrograde transport; limb development; negative regulation of smoothened signaling pathway; neural tube closure; non-motile cilium assembly; spinal cord dorsal/ventral patterning
Cellular component: ciliary basal body; ciliary transition zone; cilium; intraciliary transport particle A; membrane; ciliary tip; non-motile cilium; photoreceptor connecting cilium
Genetic constraint (gnomAD): Loss-of-function variants: 100 observed, 145.6 expected, observed/expected ratio (o/e) 0.69, 90% interval 0.58 to 0.81. The upper end of that interval is the gene's LOEUF score, 0.81, which puts it in group 3 of 6, group 1 being the genes least tolerant of losing a copy. Missense variants: 1,311 observed, 1,498.2 expected, observed/expected ratio (o/e) 0.88, 90% interval 0.83 to 0.92. Synonymous variants: 505 observed, 571.76 expected, observed/expected ratio (o/e) 0.88, 90% interval 0.82 to 0.95.
Gene-disease validity (ClinGen):
ClinGen rates the evidence that IFT122 causes each of these diseases.
cranioectodermal dysplasia 1 (autosomal recessive): Definitive.
Homologues: Orthologues: macaque IFT122 (98% identical), chimpanzee IFT122 (95% identical), dog IFT122 (93% identical), mouse Ift122 (91% identical), pig IFT122 (91% identical), rabbit IFT122 (89% identical), rat Ift122 (87% identical), guinea pig IFT122 (84% identical), tropical clawed frog ift122 (77% identical), Drosophila melanogaster Oseg1 (44% identical), Caenorhabditis elegans daf-10 (38% identical).
Diseases named in the same sentence as IFT122 in open-access papers:
IFT122 is named in the same sentence as 24 diseases in open-access papers, as found by Europe PMC text mining. Sharing a sentence is not in itself a finding about the gene and the disease. The quoted sentences say what the papers report.
cranioectodermal dysplasia (9 papers, 2014 to 2023). Cranioectodermal dysplasia (CED) is a rare developmental disorder characterized by congenital skeletal and ectodermal defects associated with dysmorphic features, nephronophthisis, hepatic fibrosis and ocular anomalies (mainly retinitis pigmentosa). "This change was the first variant found in the IFT122 gene in the family with Sensenbrenner syndrome." (PMID 35281231, 2022). "WDR35 and IFT122 genes are most commonly mutated in Sensenbrenner syndrome, and variants in the IFT140 gene are a rare cause of CED." (PMID 32007091, 2020). "To date, more than 60 patients have been reported in literature and mutations in six genes have been associated with Sensenbrenner syndrome: IFT122, WDR35, IFT140, IFT43, IFT52 and WDR19." (PMID 32007091, 2020). "The same organs are affected in an overlapping condition known as cranioectodermal dysplasia, or Sensenbrenner syndrome, which is caused by hypomorphic mutations of IFT122, another component of the IFT-B complex." (PMID 30728324, 2019). "The disorder, also called the Sensenbrenner syndrome, is characterized by craniofacial, skeletal and ectodermal abnormalities, but defects in liver, kidneys, teeth and skin have also been reported in patients with different IFT122 variants." (PMID 33606121, 2021). "On the other hand, several variants in IFT122 have been reported to cause cranioectodermal dysplasia (CED) in humans." (PMID 33606121, 2021). "Mutations in IFT122 and WDR35 are the most common cause of CED and explain about 60% of families with Sensenbrenner syndrome." (PMID 32007091, 2020). "Similarly, recessive pathogenic IFT122 variants are known to cause Cranioectodermal dysplasia 1,30 which is a nonlethal condition where patients present with craniofacial, skeletal, and ectodermal abnormalities." (PMID 29096039, 2018). "For example, Sensenbrenner syndrome (also known as cranioectodermal dysplasia), a ciliopathy characterized by sagittal craniosynostosis with accompanying facial, skeletal, and ectodermal anomalies, is caused by mutations in the IFT-A genes IFT43, WDR35, IFT122, WDR19, and IFT140." (PMID 28724397, 2017).
ciliopathies (4 papers, 2022 to 2025). "Likewise, loss of IFT122 results in ciliogenesis defects, but cilia can be rescued by the ciliopathy-associated variants such as the W7C and G513V alleles, which do not map to the TPR domains but instead to the WD40 repeats." (PMID 36346217, 2022).
retinal degeneration (3 papers, 2021 to 2024). Degeneration of the retina. "A variety of genes involved in IFT, such as Ift88, Ift122, Ift81, Ift172, and Ift52, have been reported to be associated with retinal degeneration." (PMID 36171205, 2022). "Variants in IFT122 have not been associated with retinal degeneration in mammals, but the loss of ift122 in zebrafish larvae impaired opsin transport and resulted in progressive photoreceptor degeneration." (PMID 33606121, 2021).
cutis laxa (1 paper, 2014). Cutis laxa (CL) is an inherited or acquired connective tissue disorder characterized by wrinkled, redundant and sagging inelastic skin associated with skeletal and developmental anomalies and, in some cases, with severe systemic involvement. "In a multiplex consanguineous family with typical CED features in addition to intellectual disability and severe cutis laxa, we used autozygosity-guided candidate gene analysis to identify a novel homozygous mutation in IFT122, and demonstrated impaired ciliogenesis in patient fibroblasts." (PMID 24689072, 2014).
polycystic kidney disease (1 paper, 2013). A usually autosomal dominant and less frequently autosomal recessive genetic disorder characterized by the presence of numerous cysts in the kidneys leading to end-stage renal failure. "For example, a renal-specific inactivation of Hnf1α in mice has been implicated in polycystic kidney disease and shown to mediate the down-regulation of several cystic disease genes localised to primary cilia, including Ift88 and Ift122." (PMID 23326503, 2013).
nephropathy (1 paper, 2023). A nonspecific term referring to disease or damage of the kidneys. "Defects to the IFT-A complex of proteins (e.g., WDR35, IFT122, IFT43, IFT172, IFT140 and WDR19), can present with renal disease phenotypes such as chronic renal failure, NPHP, and renal cysts and, in some cases, isolated NPHP or NPHP-like nephropathy." (PMID 38292052, 2023).
IFT122 also shares sentences with these, for which no sentence is quoted: infection (2 papers); neurodegenerative disease (2); retinitis pigmentosa (2); Alzheimer disease (1); autoimmune disease (1); breast carcinoma (1); cancer (1); colorectal cancer (1); cystic kidneys (1); dysplasia (1); ectodermal dysplasia (1); genetic disease (1); Intellectual disability (1); Leber congenital amaurosis (1); primordial dwarfism (1); schizophrenia (1); skeletal dysplasia (1); tumor (1).